IDH1 (isocitrate dehydrogenase (NADP(+)) 1)
Diseases named in the same sentence as IDH1 in open-access papers (continued):
Sharing a sentence is not in itself a finding about the gene and the disease.
tumor (continued). "The 2-HG concentration was particularly low in one of the two IDH1 tumor patients with a negative MR spectroscopy (patient 7), namely 0.29 mmoles/kg." (PMID 37685329, 2023). "This was a clinically relevant finding, as radiation therapy failed to prolong survival in the IDH1-mutant tumor-bearing mice, but pharmacological inhibition of DDR prolonged survival due to radiosensitivity." (PMID 36765553, 2023). "As in previous trials, immune responding patients with wild-type IDH1 (those exhibiting ≥50% increased IFNγ tumor antigen response post-vaccine without IDH1R132H) showed significantly increased progression-free survival (PFS) after DC vaccination." (PMID 37161052, 2023). "After ivosidenib treatment, the survival of mice bearing CT26 tumor did not change significantly, while the survival of mice bearing CT26 tumor with an IDH1 mutation was prolonged." (PMID 37741882, 2023). "Furthermore, both Forma Therapeutics’ FT2102 and Bayer’s BAY1436032 target IDH1 R132 tumors (R132X for BAY1436032), with trials actively enrolling patients across several tumor types, including GBM (NCT03684811 and NCT02746081)." (PMID 38201528, 2023). "Consistently, CRISPR-mediated deletion of HIF1α and HIF2α showed no tumor inhibitory activities against IDH1 mutant iCCA cells." (PMID 37311747, 2023). "By definition, glioblastomas are IDH-wildtype and H3-wildtype tumours, thus immunoreactivity for IDH1 R132H and H3 p.K28M (K27M) is negative." (PMID 37239289, 2023). "In contrast to IDH1 and IDH2, no tumour-associated mutations for any IDH3 genes (IDH3A, IDH3B and IDH3G) have been reported." (PMID 37296846, 2023). "Previous studies of CS have treated IDH1 and IDH2 tumours as one group." (PMID 36042521, 2022). "Among 492 PRAD patients, only IDH1 transcript levels were higher in the tumor tissue than in the nontumor tissue." (PMID 35132321, 2022). "These tumor biomarker subgroup assessments (IDH1 and MGMT) were not performed in the EF-11 study (non-comparable)." (PMID 36239858, 2022). "BRAF, ATRX, IDH1, and CDKN2A showed significant SNV alterations in most tumour types." (PMID 36186436, 2022). "Furthermore, the correlation between IDH1 expression and immune cell marker genes implies a role for IDH1 in regulating PRAD tumor immunology." (PMID 35132321, 2022). "Furthermore, the present investigation exclusively focused on IDH1 wild-type glioblastomas, due to potential molecular relationships between the IDH genotypes and tumor fluorescence." (PMID 35565263, 2022). "In addition, FT2102 (Forma Therapeutics) and BAY1436032 (Bayer) also target IDH1 R132 tumors (R132X for BAY1436032), and occurring trials are selecting patients with various tumor forms, including GBM (NCT03684811 and NCT02746081)." (PMID 35912242, 2022). "This is reassuring since the majority of neoplasms that do not carry driver alterations within strong epigenomic modifiers (e.g., IDH1/2, SMARCB1) largely retain epigenomic features of their precursor lineages." (PMID 35158935, 2022). "It was reported that 2-hydroxyglutarate (2-HG), which is generated by IDH1 MUT GBM cell’s glycolysis, could influence the tumor microenvironment and pH value and further suppress the action of immune cells." (PMID 36389748, 2022). "In addition, increased expression of isocitrate-dehydrogenase 1 (IDH1), another suppressor of tumorigenesis, and of phosphorylated and activated MOB1 (pT35), a member of the Hippo pathway, was observed in hot tumor samples." (PMID 36139700, 2022).
tumor (continued). "Using all available clinical information (n = 342), we found that IDH2 tumours tended to be larger at time of presentation (IDH1 vs IDH2: p = 0.001, IDH1 vs IDHwt: p = 0.4), supporting the premise that these tumours evolve over longer time periods, and present in older people." (PMID 36042521, 2022). "Because IDH1/2 mutations maintain through tumor recurrence, the secondary tumor with IDH1/2 wild-type was no recurrence from the primary tumor with IDH2 mutation but was a de novo tumor that was most likely to be related to the previous exposure." (PMID 35505351, 2022). "Based on the finding that TERT leads to different outcomes in IDH1- and IDH2-mutant tumours, we propose that genetic testing for IDH1, IDH2, and TERT promoter mutations in the context of other clinical factors, could be useful in patient stratification." (PMID 36042521, 2022). "Indeed, GSK864, a compound initially identified as a potent inhibitor of mutant IDH1 in AML, inhibits wild-type IDH1 activity, reduces GBM stem-like cell frequency and increases survival of tumor-bearing mice." (PMID 34764443, 2022). "In the absence of glucose in mouse mammary tumors, malic enzyme 1/IDH1 knockdown in combination strongly inhibited tumor growth by reducing NADPH production." (PMID 36497259, 2022). "However, the VASH1 expression level was correlated with tumor recurrence, WHO grade, and IDH1 wild-type expression level (P < 0.05)." (PMID 36504559, 2022). "GD was highly enriched in IDHwt tumours (GD%, IDH1: 24%, IDH2: 9%, IDHwt: 63%, IDHwt vs IDH1 p = 0.0005), and HP was exclusive to this group (HP%, IDH1: 0%, IDH2: 0%, IDHwt: 37%, IDHwt vs IDH1 p = 8e-5)." (PMID 36042521, 2022). "However, the reductive carboxylation catalyzed by IDH1 and IDH2 only occurred in anchorage-independent tumor cells, cells with altered mitochondria, or located in hypoxic niches." (PMID 34764443, 2022). "This association was observed in G2/3 (IDH1 vs IDH2: p = 7e−6) but not in DD CS (IDH1 vs IDH2: p > 0.99), implying that although TERT is associated with high-grade tumours, this is not equal in the context of IDH mutation status." (PMID 36042521, 2022). "However, utilising the larger numbers available in this study, we found 3468 differentially methylated probes (DMPs) across IDH1 and IDH2 tumours, excluding DD CS (n = 31, p = 0.002)." (PMID 36042521, 2022). "Several established targets have multiple clinical compounds in later stages of development across a variety of tumor types (e.g., IDO1, IDH1), while many earlier-phase studies are being initiated with first-in-class agents targeting metabolic nodes not yet explored (e.g., IACS-010759, opaganib)." (PMID 34981784, 2022). "This trend is observed both for adjacent noncancerous tissues and for tumor tissue, however, the difference between the Wild type IDH1 group is not significant." (PMID 35625744, 2022). "Tumor cells were positive for MGMT and IDH1, with a proliferation activity of 4% for Ki-67." (PMID 35991838, 2022). "We found, after correcting for tumor volume and location, correlations between the expression level of CD3 or IDH-1 and psychomotor speed; IDH-1, BDNF, ATRX, CK2Beta, GAT-3, NLGN3, SRF, or EAAT1 and memory performance, and P-STAT5b, NLGN3, CK2Beta, or IDH-1 and executive functioning." (PMID 35148403, 2022). "Tumor cells were positive for MGMT, IDH1, and H3K27M, with Ki-67 of 7%." (PMID 35991838, 2022). "Pathological and genetic examination confirmed that all tumor foci from the three mGBM patients were primary GBM featured with gain of chr.7 and loss of chr.10, lacking IDH1/2 mutations, high frequency of TERT promoter mutation." (PMID 34987659, 2022). "High EZH2 expression was significantly correlated with older age (p = 0.003), higher tumour grade (p < 0.001), negative IDH1 R132H immunoexpression (p = 0.039), a poor 5-year PFS (mean = 9.7 months, p < 0.001) and 5-year OS (mean = 28.2 months, p = 0.007)." (PMID 36292072, 2022).
tumor (continued). "In one tumour tissue, cytogenomic analysis revealed CN-LOH 17p and IDH1 gene mutation without typical GBM changes." (PMID 34282761, 2021). "In view of the young age of the patient, negative IDH1 R132H mutant protein and loss of ATRX expression in the tumor cells, IDH1/2 Sanger sequencing was performed to look for a noncanonical IDH mutation." (PMID 34647024, 2021). "In addition, in patients with IDH1/2 mutant IHCC, the circulating level of 2-HG is directly related to tumor burden." (PMID 33981605, 2021). "Furthermore, we performed comparison, taking into account tumor localization to the SVZ, IDH1 status, and WHO grade, respectively." (PMID 34490090, 2021). "Based on the results of preclinical studies, future randomized clinical trials should be designed to evaluate vitamin C activity in specific tumor molecular subtypes, such as those characterized by HIF-1α over-expression and TET2, L2HGDH, IDH1/2, or WT1 altered pathways." (PMID 33804775, 2021). "We demonstrated in the current study that patients of IDH1 mutation concurrent with tumor-SVZ distance >10 mm have the best clinical outcome compared with patients bearing wild-type IDH1 and tumor-SVZ distance <10 mm, which exhibit the poorest survival time and shorter tumor relapse." (PMID 34490090, 2021). "Baseline dexamethasone use as well as lack of tumor MGMT methylation and IDH1 mutation correlated with poorer OS." (PMID 33810532, 2021). "We provide further evidence that screening for the presence of IDH1‐ and IDH2‐mutant molecules in plasma from patients with central cartilaginous tumours leads to a more accurate grade and prognosis, when interpreted in the context of imaging and anatomical site, than currently provided." (PMID 34528398, 2021). "In vitro studies also showed that IDH1 mutation-derived transcriptional silencing of the ligand NKG2DL led to NK cell tolerance toward the tumor and lack of tumor-cell lysis by the innate immune cells." (PMID 33766119, 2021). "Three patients with isocitrate dehydrogenase 1 (IDH1)-mutant tumours had better PFS (5.5 months versus 1.2 months) and slight better OS (16.0 months versus 2.7 months) than patients who had IDH1-wild-type tumours." (PMID 33680090, 2021). "Tumor-SVZ distance showed no obvious interaction with the OS and PFS of patients with IDH1 mutations." (PMID 34490090, 2021). "One of these tumours (ID3) also harboured the rare IDH2 pArg172lle mutation which our ddPCR assay was not designed to detect: the other two tumours (ID24 and ID38) were WT for IDH1 and IDH2 mutations." (PMID 34528398, 2021). "To ascertain that these cells were tumoral and not cells of the tumour environment, we performed double labelling for pSTAT3 and proteins which are frequently altered in DLGG, namely the mutated form of IDH1 (R132H) and loss of ATRX." (PMID 32218467, 2020). "Sex, age, and tumor location and IDH-1 expression status were not significantly different between the paraventricular recurrence group and the nonparaventricular recurrence group." (PMID 33585189, 2020).
tumor (continued). "Control mice not receiving human tumor cells showed no positive cells for human-specific antigens, IDH1, Ki67 or ATRX (data not shown)." (PMID 32698368, 2020). "After adjustment for WHO grade, MGMT, Ki67, and TERT, molecular group of IDH1 and ATRX were associated with tumor growth in univariable analysis but not in the multivariable model." (PMID 32388499, 2020). "The IDH1 and ATRX molecular group was associated with tumor growth in univariable analysis but not in multivariable analysis, which only demonstrated a marked separation in survival in the astrocytoma with 1p/19q LOH and IDH mutation." (PMID 32388499, 2020). "Finally, a combinational analysis was performed to estimate the importance of tumoral and exosomal miR-181 levels, IDH1 and MGMT status, tumor related symptoms, quality of life index, and functional patients’ status for the survival outcome prediction." (PMID 33050332, 2020). "Based on our findings, it is possible that co-administration of inhibitors of MEK, PI3K, mTOR, IDH1, EZH2 or CDK4/6 (to target CDKN2A deletion) may have been effective in slowing or reducing tumour progression." (PMID 33053751, 2020). "Staining using a mutation-specific (R132H) antibody against isocitrate dehydrogenase 1 (IDH1), indicative for IDH-mutated astrocytomas and oligodendrogliomas, revealed no specific reaction in the present tumor (not shown)." (PMID 32103286, 2020). "However, the association of higher rates of total surgical resections in IDH1 mutated malignant astrocytoma due to the clinical factors such as younger age, frontal location, and a non-enhancing disease component in the tumor mass may also contribute to better OS." (PMID 32650387, 2020). "IDH1 inactivation with shRNAs or GSK864 (an IDH1 inhibitor) decreases GBM cell growth, promotes a more differentiated tumor cell state, increases apoptosis in response to receptor tyrosine kinase inhibitors, and prolongs the survival of patient-derived xenografts mice." (PMID 31010244, 2019). "Other pathologic and molecular tumor biomarkers, such as epidermal growth factor receptor (EGFR) amplification, aldehyde dehydrogenase 1A3 (ALDH1A3), and isocitrate dehydrogenase (IDH1/IDH2) isoforms are current foci of research and have been linked to prognosis." (PMID 31882968, 2019). "This study aimed to unravel the 2-HG independent effects of mutant IDH1 on the redox state, metabolism, and energy homeostasis in both tumor and non-neoplastic glial cells." (PMID 31888244, 2019). "Therefore we aimed to confirm whether IDH1/2 mutation induced hyper- and hypomethylation showed similar effect on promoters, enhancers and gene bodies across all six IDH1/2 mutated cancer types including tumors in which we did not have the wild-type tumor or normal tissue for comparison." (PMID 31727977, 2019). "Unfortunately, the tumor map does not find IDH1, whereas the Xena browser’s heatmap view yields frequency and variance differences for IDH1 depending on the age." (PMID 30675185, 2019). "A total of 97 (85.9%) and 77 (68.2%) tumor tissues exhibited positive immunohistochemical staining for Beclin-1 and ARID1A, respectively; 96 (85.0%) and 105 (92.9%) samples stained positive for CA9 and IDH1, respectively." (PMID 30849962, 2019). "Clinical trials have begun after preclinical studies demonstrated the efficacy of small molecule inhibitors against mutant forms of IDH1 and IDH2 accompanied by a reduction of (R)-2-HG levels, which resulted in a block of de-differentiation and growth suppression of AML tumor cells." (PMID 31105869, 2019). "Moreover, our analysis identifies consistent cross-cancer effects for 4 genes (FGFR1, ERRB2, IDH1, KRAS/NRAS) in 11 histological tumor types." (PMID 30442178, 2018). "Decision curve analysis confirmed that ZEB1 status with or without IDH1 was more beneficial to clinical decision making than conventional information such as age and tumor grade." (PMID 30705664, 2018).
tumor (continued). "To address these issues, we have performed a metabolic analysis on a cohort of patient-derived IDH1 mutant and IDH wildtype tumor cells to determine differences between these groups that may potentially be exploitable for therapy." (PMID 29692895, 2018). "As no normalization was performed on the unnormalized data to compare the mean tumor activity between IDH1 wild-type and IDH1 mutant, it has been checked (data not shown) that activity was not statistically different between both PET/CT scanners." (PMID 29953478, 2018). "From this cohort, 4 out of 5 of the proteins (IDH1, CTSD, PRDX6, and SERPINB6) also showed a statistically significant increase in abundance (12, 2.3, 2.6, and 3-fold, respectively) in the patient tumour samples when compared to the PDX F1 generation in the species-indistinguishable study." (PMID 30404163, 2018). "Moreover, our analysis identifies consistent cross-cancer effects for 4 genes (FGFR1, ERRB2, IDH1, KRAS/NRAS) in 14 tumor types." (PMID 30442178, 2018). "IDH1 and IDH2, the cytoplasmic and mitochondrial isoforms respectively, had lower levels of expression in the tumours derived from mtDNA-depleted cells than GBM100 tumours." (PMID 30208958, 2018). "The vehicle + ABT group was indistinguishable from the vehicle alone group (i.e. without ABT, P = 0.99), demonstrating that the observed anti-tumor efficacy was mediated by our IDH1 mutant-selective compounds rather than ABT." (PMID 29062039, 2017). "Together, these findings culminated in the authors recommending assessment of both IDH and ATRX status and sequencing for both IDH1/2 and H3F3A for any age group when a tumor is found to have ATRX loss and lacking IDH1/2 mutations by immunohistochemistry." (PMID 29034211, 2017). "More aggressive resection involving the whole tumor (both enhancing and nonenhancing part) correlated with better prognosis in patients with IDH1 mutant GBMs rather than with wild-type IDH1." (PMID 28316990, 2017). "We therefore performed immunofluorescent double labeling of ZEB1 and IDH1 R132H in four IDH-mutant GBM cases and quantified colocalization after blinded manual scoring of individual nuclei from at least three fields of views per tumor." (PMID 28945795, 2017). "This article will discuss why, unlike IDH1 and 2, mutations in IDH3 in tumor are not likely to be driver ones." (PMID 28785398, 2017). "The tumor cells were negative for IDH1-R132H and histone H3-K27M mutant proteins by immunohistochemistry." (PMID 28699883, 2017). "Before the treatment, the tumor volume of BCAT1 sh#1 rats was smaller than IDH1 WT rats at initial without statistical significance (9.64 mm3 [IQR, 7.70–32.28] vs 27.77 mm3 [21.12–45.15]; p = 0.1797)." (PMID 27626306, 2016). "The tumor cell proliferation and vascularity, which were evaluated by KI-67 and CD34, respectively, were markedly decreased in BCAT1 sh#1 rats than IDH1 WT rats (5.48% [IQR,–0.04–11.00] vs 33.86% [23.56–44.18]; p = 0.0001, and 1.22% [IQR, 0.71–1.72] vs 5.20% [2.44–7.95]; p = 0.0044, respectively)." (PMID 27626306, 2016). "Importantly, when analyzing IDH1 mt patients only, TTR was significantly increased along with smaller residual tumor volumes." (PMID 27344556, 2016). "A bioinformatics analysis revealed a strong correlation between TNC mRNA upregulation and expression of hypoxia-induced genes in both WT and R132H IDH1 patient GBMs, and expression of carbonic anhydrase 9 (CA9), a HIF1α-target gene, was reduced in R132H tumours." (PMID 27820599, 2016). "In addition, Kaplan–Meier analysis showed that patients with lower IDH1-R132H expression, higher preoperative CEA level, and more advanced tumor stage have shorter survival time." (PMID 27655638, 2016).